TMCO1 (transmembrane and coiled-coil domains 1)
Diseases named in the same sentence as TMCO1 in open-access papers (continued):
Sharing a sentence is not in itself a finding about the gene and the disease.
Ataxia (1 paper, 2022). Ataxia refers to impaired coordination of voluntary muscle movement. "Frameshift mutations in Tmco1 gene can cause an autosomal-recessive TMCO1-defect syndrome, characterized by distinctive craniofacial skeletal anomalies, mental retardation, ataxia, and many other clinical symptoms." (PMID 35927240, 2022).
bladder urothelial carcinoma (1 paper, 2024). "Notably, research has indicated a correlation between the downregulation of TMCO1 and an adverse prognosis in patients with bladder urothelial carcinoma (UBUC)." (PMID 39479348, 2024).
developmental delays (1 paper, 2025). "Indeed, mutations or deletions in the TMCO1 gene can result in TMCO1 deficiency syndrome, a clinical phenotype highly consistent among multiple patients, characterized by developmental delay, typical craniofacial deformities, and skeletal abnormalities." (PMID 40867644, 2025). "Furthermore, frameshift mutations in the TMCO1 gene can lead to syndromes such as craniofacial malformations, skeletal abnormalities, and developmental delays." (PMID 40867644, 2025).
hydronephrosis (1 paper, 2012). Collection of urine in the renal pelvis that results in dilatation of the renal pelvis and calyces. "A homozygous frameshift mutation in TMCO1 has been associated with a genetic syndrome involving multiple organ systems, including renal agenesis and hydronephrosis." (PMID 22570627, 2012).
Intellectual disability (1 paper, 2023). "Homozygous frameshift mutation in the transmembrane and coiled-coil domain-containing protein 1 (TMCO1) gene was identified in 11 patients from the Amish community and responsible for their congenital anomalies including craniofacial dysmorphism, skeletal malformation, and intellectual disability." (PMID 37508534, 2023).
intellectual disability syndrome (1 paper, 2022). "Bi-allelic loss-of-function variants in TMCO1 are associated with Craniofacial dysmorphism, skeletal anomalies, and intellectual disability syndrome (CFSMR; MIM: 213980)." (PMID 36186440, 2022).
melanoma (1 paper, 2012). A malignant, usually aggressive tumor composed of atypical, neoplastic melanocytes. "The expression levels in metastatic melanoma tumours of two of these genes (UBE2S and TMCO1) appear to be significantly associated with the time to relapse in melanoma patients." (PMID 22536322, 2012).
normal tension glaucoma (1 paper, 2012). "We observed expression of seven genes which were previously genetically associated with POAG (included normal tension glaucoma (NTG)), namely APOE, CAV1, EDNRA, MYOC, OPTC and TMCO1." (PMID 23028713, 2012).
renal carcinoma (1 paper, 2015). A carcinoma arising from the epithelium of the renal parenchyma or the renal pelvis. "We also made use of TCGA clear cell data to examine the frequency of mutation of ALDH9A1, MGST3, LOC440700 and TMCO1 in renal cancer." (PMID 25826619, 2015).
cancer (7 papers, 2016 to 2025). A tumor composed of atypical neoplastic, often pleomorphic cells that invade other tissues. "In many ways, TMCO1 mimics some of the features of leaky IP3Rs, which are linked to the remodelling of cell death pathways in cancer cells." (PMID 39353922, 2024). "We therefore assessed the potential of TMCO1 silencing to promote cancer cell death induced by agents that are sensitive to endoplasmic reticulum Ca2+ levels." (PMID 39353922, 2024). "Using LC-MS/MS proteomics, we found a novel interaction between TMCO1 and nuclear transport proteins, including KPNB1 and IPO7, which are associated with several cancers." (PMID 39353922, 2024). "In summary, these studies suggest that TMCO1 may play either a pro-cancer or anti-cancer role in various cancers, influencing cancer cell proliferation, apoptosis, and immune response." (PMID 40867644, 2025). "In our study, TMCO1 plays an oncogenic role in tumorigenesis, potentially through the modulation of calcium ion homeostasis, which in turn affects the biological behaviors of cancer cells." (PMID 39479348, 2024). "Furthermore, the interaction between iASPP and TMCO1 could offer novel therapeutic strategies for cancer treatment." (PMID 39479348, 2024).
tumor (6 papers, 2012 to 2025). "Our studies showed that, similar to patient data, the expression of upregulated genes CACNA1H and TMCO1 is increased in GTML tumour tissues compared to the control mice cerebellum tissues." (PMID 34573310, 2021). "TMCO1, a novel tumor suppressor, dysregulated cell-cycle progression via suppression of the AKT pathway in UBUCs." (PMID 34204134, 2021). "By specifically suppressing iASPP expression, the levels of TMCO1 protein may be diminished, calcium ion homeostasis could be reestablished, and consequently, tumor progression might be curtailed." (PMID 39479348, 2024). "The role of TMCO1 in tumor cells is complex and varied, and it may play different roles in different tumor types." (PMID 39479348, 2024). "Given their roles in calcium ion homeostasis, the influence of TMCO1 and CALR on the tumor immune microenvironment deserves deeper examination." (PMID 39479348, 2024). "In this study, we identified three tumor antigens, CCR4, TMCO1, and SPACA4, related to the prognosis and antigen-presenting cell infiltration of HNSCC." (PMID 36671475, 2022). "This study determined that CCR4, TMCO1, and SPACA4 may be potential antigens for HNSCC mRNA tumor vaccine development, and patients with immune subtype C3 might benefit most from mRNA vaccination." (PMID 36671475, 2022). "Three tumor antigens (CCR4, TMCO1, and SPACA4) related to APCs infiltration and prognosis in HNSCC were identified, and it is expected that these genes might become candidate antigens for an mRNA vaccine." (PMID 36671475, 2022). "Furthermore, CCR4 was significantly correlated with tumor infiltration of B cells, CD8+ T cells, CD4+ T cells, and macrophages, while TMCO1 was significantly correlated with CD8+ T cells, and SPACA4 was significantly correlated with B cells, CD8+ T cells and Neutrophils." (PMID 36671475, 2022).
TMCO1 also shares sentences with these, for which no sentence is quoted: atrial fibrillation (1 paper); breast tumours (1); colon cancer (1); head and neck squamous cell carcinoma (1); lung adenocarcinoma (1); metastatic melanoma (1); premature ovarian failure (1); renal agenesis (1); schizophrenia (1); trichohepatoneurodevelopmental syndrome (1).